TARDBP (TAR DNA binding protein)
Diseases named in the same sentence as TARDBP in open-access papers (continued):
Sharing a sentence is not in itself a finding about the gene and the disease.
sarcoma (continued). "The most common genes associated with ALS include TDP-43 (TAR DNA-binding protein), FUS (fused in sarcoma), NEFH (ALS2 neurofilament heavy peptide), C9ORF72 (Chromosome 9 open reading frame 72), and Cu/Zn Super Oxide Dismutase 1 (SOD1)." (PMID 35327979, 2022). "These include mutant SIGMAR1 encoding the Sigma-1 receptor, mutant SOD1 encoding Cu/Zn superoxide dismutase-1 (SOD1), mutant TARDBP encoding TDP43, mutant FUS encoding fused in sarcoma and mutant C9orf72." (PMID 35693938, 2022). "For instance, inclusions containing the ubiquitinated RNA-binding proteins TDP-43 (TAR DNA-binding protein 43) or FUS (Fused in Sarcoma) can be found in patients of both diseases." (PMID 35777956, 2022). "Despite their different physiological functions, disease-related proteins like tau, α-synuclein, TAR DNA binding protein-43, fused in sarcoma and mutant huntingtin, all share low complexity regions that can mediate their liquid-liquid phase transitions." (PMID 34019093, 2021). "Different genes have been associated to ALS pathology including those encoding for Cu-Zn superoxide dismutase 1 (SOD1), Tar DNA binding-protein 43 (TDP-43), fused in sarcoma/translocated in liposarcoma (FUS), or chromosome 9 open reading frame 72 (C9orf72)." (PMID 34276318, 2021). "The mutation in C9orf72 and mutations in three other genes – TDP-43 (TAR DNA-binding protein 43), SOD1 (superoxide dismutase) and FUS (fused in sarcoma) – account for approximately two-thirds of familial ALS cases." (PMID 33495278, 2021). "Nevertheless, a number of such mutations have been reported, e.g., in the genes coding for the RNA-binding proteins FUS (fused in sarcoma) and TDP-43 (TAR DNA- binding protein 43)." (PMID 34948065, 2021). "In contrast, only 10% of ALS cases have a familial background, including the most frequently mutated genes SOD1 (superoxide dismutase 1), TDP-43 (TAR DNA binding protein) and FUS (fused in sarcoma)." (PMID 34295920, 2021). "These include mutations in Cu/Zn superoxide dismutase 1 (SOD1), TAR DNA-binding protein 43 (TDP-43) and fused in sarcoma/translated in liposarcoma (FUS), and an increased number of repeats in chromosome 9 open reading frame 72 (C9orf72)." (PMID 33089205, 2020). "In line with this, a hallmark pathology of ALS is protein deposition and inclusion formation within motor neurons and surrounding glia of the proteins TAR DNA-binding protein 43, superoxide dismutase-1, or fused in sarcoma." (PMID 33328890, 2020). "Familial ALS accounts for the remaining 10% of patients and has been linked to mutations in genes such as Cu, Zn-superoxide dismutase 1 (SOD1), chromosome 9 open reading frame 72 (C9orf72), fused in sarcoma, and TAR DNA-binding protein 43 (TDP-43)." (PMID 32570926, 2020). "This is the case for mutation in TARDBP encoding the TDP-43 protein, FUS encoding the fused in sarcoma protein, and several other ‘ALS proteins’ [reviewed in]." (PMID 31203387, 2019). "TDP-43 (Tar-DNA binding protein 43 or TARDBP) and FUS (fused in sarcoma) were the first two RNA-associated factors to be genetically linked to ALS." (PMID 29430619, 2018). "TAR DNA binding protein 43 (TDP-43) inclusions or that are fused in sarcoma/translocated in liposarcoma (FUS/TLS) are displayed and characterized as the major pathology of ALS/FTLD." (PMID 28713244, 2017). "FTD is a histopathologically heterogeneous disorder comprising tau, TAR DNA-binding protein-43, and fused in sarcoma protein pathology." (PMID 27802290, 2016). "Many other disease-causative genes have been identified, including TAR DNA-binding protein (TARDBP or TDP-43), fused in sarcoma (FUS/TLS), vesicle-associated membrane protein-associated protein B (VAPB), among others." (PMID 24324498, 2013). "These genes include SOD1, TAR DNA binding protein (TDP43), fused in sarcoma, progranulin, ubiquilin 2 and a hexanucleotide repeat expansion of a noncoding region in C9ORF72." (PMID 22457769, 2012).
sarcoma (continued). "These genes encode a variety of proteins, such as the antioxidant enzyme Cu/Zn superoxide dismutase (SOD1), and the RNA processing regulatory factors TAR DNA binding protein 43 (TDP-43) and fused in sarcoma/translocated in liposarcoma (FUS/TLS)." (PMID 22547957, 2011). "To determine whether LMNs with ALS mutations exhibit pathological phenotypes, we used four ALS-iPSC lines carrying genetic mutations in either TDP-43 (TARDBP, TAR DNA binding protein 43) or FUS (fused in sarcoma)." (PMID 39706179, 2025). "To date, more than 50 modified genes have been examined in ALS, but they are primarily linked to mutations in the SOD1, TARDBP, and FUS/TLS genes, encoding Cu/Zn superoxide dismutase-1, transactive response DNA-binding protein 43 (TDP-43), fused in sarcoma/translocated in liposarcoma, respectively." (PMID 39123408, 2024). "ALS models are commonly based on mutant superoxide dismutase 1 (SOD1), TAR DNA-binding protein 43 (TDP-43), fused in sarcoma or translocated in liposarcoma (FUS), the chromosome 9 open reading frame 72 (C9orf72) gene, ubiquilin 2 (UBQLN2), matrin 3 (MATR3), and senataxin (SETX)." (PMID 36672187, 2023). "Amongst the more than 30 ALS genes, additional important contributors to the number of ALS patients are found in the FUS gene-encoding form fused in sarcoma/translated in liposarcoma (FUS/TLS), and in the TARDBP gene-encoding transactive response DNA binding protein 43 (TDP-43)." (PMID 34359958, 2021). "In vitro, stress-granule proteins, such as TAR DNA-binding protein 43 (TDP-43), fused in sarcoma (FUS), and heterogeneous nuclear ribonucleoprotein A2/B1 (hnRNPA2/B1) form liquid droplets, then undergo gelation and may be converted into aggregated fibrils." (PMID 33469149, 2021). "In these neural disorders, two RNA-binding proteins (RBPs), TDP-43 (43 kDa TAR DNA-binding protein) and FUS (fused in sarcoma), have been reported as the common causative gene products, of which modulations lead to a gain of functional toxicity or a loss of normal protein function." (PMID 34624313, 2021). "Other mutant genes are less frequently represented in fALS: examples are the genes encoding TAR DNA-binding protein 43 (TDP-43), the ALS-linked fused in sarcoma/translocated in liposarcoma (FUS/TLS), the ubiquilin-2, the optineurin, the valosin-containing protein/p97 (VCP/p97), and others." (PMID 32792938, 2020). "However, mutations in TAR DNA-binding protein 43 (TDP-43, TARDBP), fused in sarcoma/translocated in liposarcoma (FUS/TLS), vesicle-associated membrane protein-associated protein B (VAPB) and other genes have been reported." (PMID 26858605, 2016). "Similarly, in ALS, cytoplasmic inclusions contain copper/zinc (CuZn) superoxide dismutase 1 (SOD1), TAR DNA binding protein 43 (TDP-43), or fused in sarcoma/translated in liposarcoma (FUS/TLS)." (PMID 24348565, 2013). "Also, TARDBP, which encodes TAR DNA-binding protein, and FUS, a RNA- binding protein fused in sarcoma, also contribute to FALS cases." (PMID 24367332, 2013). "The majority of ALS cases which have been reported are sporadic (SALS); 10% are familial (FALS), some of which arise from mutations in superoxide dismutase-1 (SOD1), TAR DNA-binding protein (TDP43) and fused in sarcoma/translated in liposarcoma (FUS/TLS), ALS2, dynactin, and senataxin." (PMID 26317018, 2013). "Among the genes associated with familial ALS, mutations in TAR DNA-binding protein-43 (TDP-43), fused in sarcoma/translocated in liposarcoma (FUS/TLS), optineurin and SQSTM1, and hexanucleotide repeat expansion in C9ORF72 were also identified in sporadic ALS cases." (PMID 23835137, 2013). "Clinically indistinguishable ALS can be caused by genetic mutations of Cu/Zn superoxide dismutase (SOD1), TAR-DNA binding protein 43 (TDP43), or fused in sarcoma/translocated in liposarcoma (FUS/TLS), or can occur in the absence of known mutation as sporadic disease." (PMID 22493728, 2012).
sarcoma (continued). "Additional genes that cause dominantly inherited forms of clinically typical ALS include the vesicle associated membrane protein (VAMP)-associated protein B (VAPB) (ALS8), the TAR DNA binding protein (TARDBP) and the fused in sarcoma/translated in liposarcoma (FUS/TLS)." (PMID 19479031, 2009). "For instance, the TAR DNA-binding protein of 43 kDa (TDP-43) aggregates at high pH and NaCl concentration, while fused in sarcoma (FUS) aggregates at low concentrations of RNA and in the presence of dextran and NaCl." (PMID 40811716, 2025). "TDP-43 (TAR DNA-Binding protein-43) and FUS/TLS (fused in sarcoma/translocated in liposarcoma) are two RNA-binding proteins (RBPs) with nuclear localization predominantly involved in every step of RNA metabolism regulation." (PMID 40565515, 2025). "Several genes have been implicated in familial ALS, including SOD1 (superoxide dismutase 1), C9orf72 (chromosome 9 open reading frame 72), TARDBP (TAR DNA-binding protein), FUS (fused in sarcoma), and others." (PMID 39199129, 2024). "Many studies have revealed that ALS-related RNA binding proteins (RBPs), such as TAR DNA-binding protein 43 (TDP-43) and fused in sarcoma/translocated in liposarcoma (FUS), regulate miRNAs processing in both the nucleus and cytoplasm." (PMID 36895420, 2023). "Currently, it is accepted that superoxide dismutase 1 (SOD1) and TAR DNA-binding protein 43 (TDP-43), fused in sarcoma/translocated in sarcoma (FUS) and chromosome 9 open reading frame 72 (C9ORF72), are the main contents of the neuronal inclusions." (PMID 35479082, 2022). "In this review article, we summarize the roles and risks of G4-contaning RNAs and two G4-RNA binding proteins, TDP-43 (43 kDa TAR DNA-binding protein) and FUS (fused in sarcoma)." (PMID 35898304, 2022). "More than 20 genes have been associated with the disease, including superoxide dismutase 1 (SOD1), TAR DNA binding protein (TARDBP), fused in sarcoma/translocated in liposarcoma (FUS/TLS), and C9ORF72 repeat expansions." (PMID 35455952, 2022). "fALS is genetically linked to at least 15 genes, including SOD1 (Cu/Zn superoxide dismutase), TARDBP (TAR DNA-binding protein), FUS (fused in sarcoma), ANG (angiogenin precursor), and OPTN (optineurin)." (PMID 34876200, 2021). "Deposits of fused sarcoma (FUS) and Tar DNA-binding protein 43 (TDP-43) have been reported to be hallmarks of both of these pathologies." (PMID 33672391, 2021). "Mutations on the genes, SOD1 (Cu/Zn superoxide dismutase 1), TARDBP (TAR DNA-binding protein 43), FUS/TLS (fused in sarcoma/translocated in liposarcoma), and C9ORF72 have been identified in ALS patients." (PMID 34335276, 2021). "These proteins are fused in sarcoma (FUS), heterogeneous nuclear ribonucleoprotein A1 (hnRNPA1), and the TAR DNA-binding protein 43 (TDP-43)." (PMID 34762868, 2021). "Some of these LCD containing RBPs, such as TAR DNA-binding protein 43 (TDP43) and fused in sarcoma/translated in liposarcoma (FUS/TLS), have been demonstrated to be involved in axonal mRNA transport and/or translation." (PMID 32961072, 2020). "There is a strong correlation between fALS and the mutant RNA processing protein, including Cu/Zn superoxide dismutase 1 (SOD1), TAR DNA-binding protein 43 (TDP-43), C9ORF72(C9), and fused in sarcoma." (PMID 32655368, 2020). "A number of ALS-associated proteins have been found to regulate the activity of HDAC6, specifically the proteins Fused in Sarcoma/Translocated in Sarcoma (FUS/TLS) and TAR DNA binding protein-43 (TDP-43)." (PMID 30935091, 2019). "Several other genes, including TAR DNA-binding protein 43 (TDP-43), Fused in Sarcoma/Translocated in Sarcoma (FUS/TLS), and chromosome 9 open reading frame 72 (C9ORF72), have also been found to be mutated in familial ALS patients." (PMID 29540819, 2018).
sarcoma (continued). "In 11 patients, six had phosphorylated TAR DNA-binding protein 43 (pTDP-43)-immunoreactive (ir) neuronal cytoplasmic inclusions (NCI), two had fused in sarcoma (FUS)-ir NCI, and three had copper/zinc superoxide dismutase (SOD1)-ir NCI." (PMID 27716404, 2016). "Approximately 90 % of ALS patients are sporadic whilst 10 % are familial cases with genetic mutations in SOD1 (Cu/Zn superoxide dismutase 1), FUS (fused in sarcoma), TARDBP (also known as TDP-43) and C9ORF72, among others." (PMID 26227626, 2015). "One of the proteins mutated and contributing to the development of ALS are two DNA/RNA binding proteins: TAR DNA-binding protein-43 (TDP-43) and fused in sarcoma/translocated in liposarcoma (FUS/TLS; Lagier-Tourenne and Cleveland, 2009)." (PMID 24624135, 2014). "Nearly all cases of FTLD fall into 3 categories, based on the most prominent misfolded protein detected in the pathologic aggregates: tau, TDP-43 (TAR DNA binding protein 43), and Fus (fused in sarcoma)." (PMID 22654725, 2011). "Despite the growing number and variety of these genes, four of them stand out as the most commonly mutated in ALS: superoxide dismutase 1 (SOD1), chromosome 9 open reading frame 72 (C9orf72), fused in sarcoma/translocated in liposarcoma (FUS/TLS), and TAR DNA-binding protein 43 (TARDBP-43)." (PMID 40422183, 2025). "A pathological hallmark is the presence of cytoplasmic inclusions whose major components are fused in sarcoma/translocated in liposarcoma RNA-binding protein (FUS/TLS), TAR DNA-binding protein 43 (TDP-43), and the translational product of intronic repeats in gene C9ORF72." (PMID 38397838, 2024). "Among the several genes identified as ALS-related, some are involved in both fALS and sALS, such as TDP-43 (TAR DNA-binding protein 43), also known as TARDBP (transactive response DNA-binding protein), SOD1 (copper zinc superoxide dismutase 1), C9ORF72, and FUS (fused in sarcoma), among others." (PMID 37443797, 2023). "Notably, in a sarcoma study, it was found that a four-gene signature, including DHRS3, JRK, TARDBP, and TTC3, can predict patient survival based on a real-world cohort." (PMID 36231133, 2022). "The genetic mutations such as superoxide dismutase 1 (SOD1), TAR DNA-binding protein 43 (TDP-43) and Chromosome 9 open reading frame 72 (C9ORF72), fused in sarcoma/translocated in lip sarcoma (FUS/TLS) resulting in accumulation of misfolded proteins have been linked to the disease." (PMID 31225510, 2019). "In particular, mutations in several genes including superoxide dismutase 1 (SOD1), TAR DNA-binding protein-43 (TDP-43), fused in sarcoma/translocated in liposarcoma (FUS/TLC), and/or C9orf72, are thought to contribute to the progressive degeneration of motor neurons." (PMID 29872373, 2018). "Sanger sequencing was used to screen these subjects for mutations in the coding regions of superoxide dismutase-1 (SOD1), angiogenin (ANG), fused in sarcoma/translated in liposarcoma (FUS/TLS), TAR DNA-binding protein 43 (TARDBP), and multivesicular body protein 2B (CHMP2B)." (PMID 23155438, 2012). "Its pathophysiology is complex and multifactorial involving several genetic factors which cause protein aggregation and formation of ubiquitin-positive, tau- and α-synuclein-negative TDP-43 (TAR DNA-binding protein 43), FUS (fused in sarcoma) inclusions." (PMID 26263977, 2015).
neuroblastoma (129 papers, 2010 to 2026). Neuroblastoma (NB) is the most common solid, extracranial childhood tumor. "The aim of this study was to investigate the effect of icaritin (ICT) on TAR DNA-binding protein 43 (TDP-43)-induced neuroblastoma (SH-SY5Y) cell damage and to further explore its underlying mechanisms." (PMID 34434670, 2021). "To further examine the role of TDP-43 in regulating endogenous GSK3 activity, we performed reciprocal siRNA-mediated knockdown of TARDBP in SH-SY5Y neuroblastoma cells, achieving a mean knockdown of 75% TDP-43 protein by 72 h." (PMID 41546756, 2026). "Our experiments revealed that TARDBP mRNA and MALAT1 RNA expression levels are similarly linked in the SH-SY5Y neuroblastoma cell line." (PMID 39837396, 2025). "CRISPR/Cas9-mediated fluorescent tagging of endogenous TARDBP has been reported in HEK293T cells for live-cell imaging, in human neuroblastoma cells for FRAP or in iPSCs for real-time quantification of nuclear endogenous TDP-43." (PMID 36930291, 2023). "The most highly mutated genes, such as MYC, TERT, FASLG, RIPK1, TNFSF10, TARDBP, and CDKN2A, have been well characterized in liver cancer, diffuse large B-cell lymphoma, neuroblastoma, and kidney renal clear cell carcinoma." (PMID 35875102, 2022). "To determine if hnRNP L can bind and regulate UNC13A cryptic RNA splicing in a physiological relevant cell type, we performed CLIP of hnRNP L-bound RNAs in human neuroblastoma (M17) cells in which TDP-43 has been down-regulated using siRNA targeting TARDBP (siTARDBP)." (PMID 36930682, 2023). "Among them, KuA has been shown to have strong antioxidant activity, which can significantly attenuate hydrogen peroxide (H2O2)-induced apoptosis in TAR DNA-binding protein 43 (TDP-43)-induced neuroblastoma (SH-SY5Y) cells by inhibiting oxidative stress and inactivating apoptosis signaling pathway." (PMID 35894345, 2022). "HuD was then found among the interactors of ALS-linked factors, including the RBPs Fused in sarcoma (FUS) and TAR DNA binding protein 43 (TDP-43), in neuroblastoma cells." (PMID 36498933, 2022).